NPR2 (natriuretic peptide receptor 2)
Description:
Receptor for the C-type natriuretic peptide NPPC/CNP hormone. Has guanylate cyclase activity upon binding of its ligand. May play a role in the regulation of skeletal growth.
Synonyms: GC-B; ANPRB; GUCY2B; ANPb; AMDM; ECDM; GCB; GUC2B; NPRB; NPRBi; SNSK
Tractability: Small molecule: it belongs to a druggable protein family. Antibody: UniProt places it where antibodies can reach, with high confidence; its Gene Ontology location is reachable by antibodies, with high confidence; UniProt predicts a signal peptide or a membrane-spanning region. PROTAC: ubiquitination databases record sites on it; its protein half-life has been measured. Other modalities: an approved drug acts on it.
Target class: Lyase; Enzyme; Guanylate cyclase; Receptor guanylate cyclase
Gene: Protein-coding gene on chromosome 9 (35,791,003 to 35,809,732, forward strand). Ensembl gene ENSG00000159899.
Subcellular location: Cell membrane
Pathways (Reactome):
Muscle contraction: Physiological factors
Gene Ontology:
Molecular function: guanylate cyclase activity; hormone binding; natriuretic peptide receptor activity; peptide hormone binding; protein binding; ATP binding; identical protein binding; phosphorus-oxygen lyase activity; protein kinase activity
Biological process: cellular response to granulocyte macrophage colony-stimulating factor stimulus; cGMP biosynthetic process; receptor guanylyl cyclase signaling pathway; bone growth; regulation of blood pressure; activation of meiosis involved in egg activation; axonogenesis; axonogenesis involved in innervation; blood circulation; blood vessel development; blood vessel remodeling; c-di-GMP signaling; cartilage development; cellular response to cGMP; cellular response to peptide; cGMP metabolic process; chemical synaptic transmission; chondrocyte differentiation; chondrocyte proliferation; chromosome organization; collateral sprouting; cumulus cell differentiation; cyclic nucleotide biosynthetic process; digestive tract development; digestive tract morphogenesis; and 37 more
Cellular component: plasma membrane; cilium; cytoplasm; membrane; neuron projection; nucleus; synapse
Genetic constraint (gnomAD): Loss-of-function variants: 45 observed, 111.62 expected, observed/expected ratio (o/e) 0.4, 90% interval 0.32 to 0.52. The upper end of that interval is the gene's LOEUF score, 0.52, which puts it in group 2 of 6, group 1 being the genes least tolerant of losing a copy. Missense variants: 864 observed, 1,321.7 expected, observed/expected ratio (o/e) 0.65, 90% interval 0.62 to 0.69. Synonymous variants: 460 observed, 511 expected, observed/expected ratio (o/e) 0.9, 90% interval 0.83 to 0.97.
Homologues: Orthologues: macaque NPR2 (99% identical), chimpanzee NPR2 (99% identical), dog NPR2 (99% identical), pig NPR2 (99% identical), mouse Npr2 (99% identical), guinea pig NPR2 (98% identical), rat Npr2 (96% identical), rabbit NPR2 (95% identical), tropical clawed frog npr2 (75% identical), zebrafish npr1a (59% identical), zebrafish npr1b (57% identical). Paralogues in human: NPR1 (61% identical), GUCY2F (34% identical), GUCY2D (33% identical), GUCY2C (30% identical), GUCY1A2 (18% identical), ADCY6 (16% identical), ADCY2 (16% identical), ADCY5 (16% identical), GUCY1A1 (16% identical), ADCY4 (16% identical), ADCY8 (16% identical), ADCY7 (16% identical), and 5 more.
Diseases named in the same sentence as NPR2 in open-access papers:
NPR2 is named in the same sentence as 80 diseases in open-access papers, as found by Europe PMC text mining. Sharing a sentence is not in itself a finding about the gene and the disease. The quoted sentences say what the papers report.
dwarfism (17 papers, 2012 to 2023). "Mouse models with Npr2 loss-of-function mutations or with disruption of the CNP gene (Nppc) also show severe dwarfism, and an Npr2 gain-of-function mutation causes overgrowth." (PMID 33986191, 2021). "Total or chondrocyte-specific genetic deletion of Nppc (the gene encoding CNP) or Npr2 in mice severely impairs endochondral ossification, resulting in dwarfism characterized by shortening of the vertebrae, long bones, and skull." (PMID 30048539, 2018). "Loss-of-function mutations in the human NPR2 gene result in short stature and the dwarfism syndrome acromesomelic dysplasia, Maroteaux type." (PMID 30048539, 2018). "Both activating mutations in fibroblast growth factor receptor 3 (FGFR3) and inactivating mutations of guanylyl cyclase B (GC-B), also called NPRB or NPR2, cause human dwarfism." (PMID 29035170, 2017). "A spontaneous loss-of-function mutation of mouse Npr2 causes severe disproportionate dwarfism, while a gain-of-function mutation of NPR2 producing excessive cGMP causes human overgrowth disorder." (PMID 26306008, 2015). "To determine the role of CNP/NPR-B signaling in male reproduction we investigated phenotype of Npr2-deficient short-limbed-dwarfism (Npr2slw/slw) mice, which have been shown to have gastrointestinal (GI) abnormalities." (PMID 25012822, 2014). "At least two studies have shown that mutations in GC-binding domain in the gene Npr2 result in impaired endochondral ossification and severe dwarfism in mice." (PMID 22691581, 2012). "The original mouse models of disrupted Nppc or Npr2 expression described dwarfism and early death phenotypes." (PMID 37629102, 2023). "Npr1 null animals show hypertension, ventricular fibrosis and cardiac hypertrophy, while Npr2 mutant animals are affected by dwarfism, due to impaired endochondral ossification, and female infertility." (PMID 37162198, 2023). "Mice with induced models of Nppc or Npr2 deletion display profound achondroplasia, dwarfism and early death." (PMID 37629102, 2023). "A distinct NPR2-knockout mouse model harboring a 4-bp deletion in exon 3 exhibited dwarfism and female sterility with normal pituitary and uterine function." (PMID 35368703, 2022). "It should be noted that Npr2 mutant mice exhibit additional abnormalities, including dwarfism and cardiac deficits that compromise their health and often cause them to die within the first postnatal month." (PMID 25473838, 2014). "On the contrary, disruption of Nppc or Npr-2 genes proved to lead to dwarfism and severe skeletal malformations in mice." (PMID 23805197, 2013).
achondroplasia (12 papers, 2014 to 2025). Achondroplasia is the most common form of chondrodysplasia, characterized by rhizomelia, exaggerated lumbar lordosis, brachydactyly, and macrocephaly with frontal bossing and midface hypoplasia. "For example, achondroplasia caused by a mutation in the fibroblast growth factor receptor 3 gene, a negative regulator of bone growth, now has an natriuretic peptide receptor 2 (NPR2) agonist (Vosoritide) developed as treatment." (PMID 33658983, 2020). "Since NPR2 is mutated in human patients with achondroplasia, a deeper understanding of the Npr2 phenotype in an animal model is needed." (PMID 25473838, 2014). "Interestingly, NPR2 mutations cause achondroplasia in humans, suggesting that closer examination of auditory function may be warranted in such patients." (PMID 25473838, 2014). "Transgenic mouse models of disrupted Nppc or Npr2 expression are phenotypically similar, and exhibit profound growth abnormalities; specifically, these mice exhibit achondroplasia due to impaired endochondral ossification, leading to pronounced dwarfism with early death in 90% of these cohorts." (PMID 37629102, 2023). "Ongoing clinical trials have shown that in patients with achondroplasia, in which skeletal dysplasia is caused by a constitutively active form of FGFR3, stimulation of NPR2 by subcutaneous injection of a hydrolysis-resistant analog of CNP increases bone length." (PMID 29199951, 2017). "CNP levels are elevated in patients with achondroplasia, suggesting that NPR2 in their chondrocytes is resistant to CNP, which could be due to NPR2 dephosphorylation." (PMID 29199951, 2017). "Elevated levels of CNP and NT-proCNP in achondroplasia are thought to be a natural response of the human body to this overactivation of the MEK/ERK MAPK pathway in chondrocytes, which functionally inhibits the effect of CNP on chondrocytes via NPR-B encoded by NPR2." (PMID 40430081, 2025). "Thus, if NPR2 phosphorylation could be increased in chondrocytes of these patients, by inhibiting the phosphatase that dephosphorylates NPR2, this could potentially enhance the therapeutic stimulation of NPR2 activity by CNP as a treatment for achondroplasia." (PMID 29199951, 2017). "Besides that, a CNP analog named vosoritide, that has been used as an experimental drug for the treatment of achondroplasia, can be in the future an option to treat children with nonsyndromic short stature, especially those with heterozygous mutations in the NPR2 or in the NPPC genes." (PMID 30864634, 2019).
acromesomelic dysplasia (12 papers, 2012 to 2025). A group of extremely rare, inherited, progressive skeletal conditions that result in a particular form of short stature, called short-limb dwarfism. "In clinical studies, inactivating mutations of NPR2 were found to cause a rare form of extreme short stature, called acromesomelic dysplasia, type Maroteaux." (PMID 33986191, 2021). "Homozygous inactivating mutations of NPR2 caused a severe skeletal dysplasia, acromesomelic dysplasia and Maroteaux type." (PMID 31805863, 2019). "We have reported two novel mutations in the gene NPR2, which result in Acromesomelic Dysplasia, type Maroteaux (AMDM)." (PMID 22691581, 2012). "Biallelic LoF variants in NPR2 are known to cause autosomal recessive (AR) acromesomelic dysplasia, Maroteaux type (AMDM; MIM: 602875), an endochondral bone growth disorder characterized by significant short stature, predominantly affecting the forearms and hands." (PMID 36035248, 2022). "NPR-B is encoded by NPR2, biallelic variants in which are responsible for acromesomelic dysplasia, Maroteaux type (AMDM; MIM 602875)." (PMID 34782440, 2022).
acromesomelic dysplasia type Maroteaux (11 papers, 2012 to 2022). "Biallelic variations of NPR2 mutation can cause acromesomelic dysplasia, Maroteaux type (AMDM) (MIM #602875), while monoallelic variants result in short stature with non-specific skeletal deformities and Miura-type osteochondral dysplasia." (PMID 35250876, 2022). "Inactive mutations of the CNP receptor gene (NPR2) cause acromesomelic dysplasia type Maroteaux (homozygous mutations)." (PMID 36611397, 2022). "Dominant negative and gain-of-function mutations in NPR2, the gene encoding NPR-B, are responsible for short and tall stature phenotype, such as in acromesomelic dysplasia type Maroteaux and tall stature with long halluces type NPR2, respectively." (PMID 33919228, 2021). "In humans, loss-of-function mutations in the NPR2 gene cause a skeletal dysplasia, termed acromesomelic dysplasia type Maroteaux (AMDM) with an extremely short and disproportionate stature." (PMID 29472841, 2018). "The gene abnormality in the cn/cn mouse is a loss-of-function mutation in the natriuretic peptide receptor 2 (NPR-2), the same abnormality detected in the human skeletal dysplasia, acromesomelic dysplasia Maroteaux type (AMDM)." (PMID 25319082, 2014). "Loss-of-function mutations in NPR2 encoding a receptor for CNP are responsible for acromesomelic dysplasia Maroteaux-type (AMDM), a form of short-limbed human skeletal dysplasias." (PMID 24324705, 2013). "Mutations in the gene NPR2 have been shown to cause acromesomelic dysplasia-type Maroteaux (AMDM), an autosomal recessive skeletal disproportionate dwarfism disorder in humans." (PMID 22691581, 2012). "Therefore, in humans and in mice loss-of-function mutations in the NPR2 gene cause a skeletal dysplasia, termed acromesomelic dysplasia type Maroteaux (AMDM; OMIM602875) with an extremely short and disproportionate stature." (PMID 29962937, 2018).
cardiac hypertrophy (8 papers, 2016 to 2024). "Although both receptors protect from cardiac hypertrophy, their effects on contractility are markedly different, from little effect (NPR1) to pronounced negative inotropic and positive lusitropic responses (NPR2) with unclear underlying mechanisms." (PMID 29934640, 2018).
Hypertension (7 papers, 2016 to 2025). The presence of chronic increased pressure in the systemic arterial system. "Deletion of Npr1 (NPR-A) in mice leads to hypertension, hypertrophy, and cardiac fibrosis, whereas genetic ablation of Npr2 (NPR-B) results in dwarfism and female sterility." (PMID 38891063, 2024).
heart failure (5 papers, 2016 to 2022). Inability of the heart to pump blood at an adequate rate to meet tissue metabolic requirements. "Moreover, a vital cardioprotective role was recently demonstrated for the CNP receptor NPR-B, as heterozygous Npr2 KO mice develop heart failure with myocardial fibrosis in advanced age62." (PMID 35013221, 2022).
breast carcinoma (3 papers, 2007 to 2022). "With regard to NRPs, the expression of NRP-1 mRNA was found to be ubiquitous in all the tested human breast cancer cell lines, whereas NPR-2 mRNA was expressed only by high COX-2 and VEGF-C expressing MDA-MB-231 and Hs578T cells." (PMID 17912247, 2007). "Collectively, our studies illustrate the dynamic nature of NRP2 isoform expression in breast cancer and suggest that targeting NPR2 isoform-specific signaling pathways or NRP2-isoform expressing TAM subsets may be leveraged for macrophage reprograming or TAM-targeted immunotherapies." (PMID 35651620, 2022).
female infertility (3 papers, 2014 to 2023). Diminished or absent ability of a female to achieve conception. "Targeted disruption of the Nppc or Npr2 genes (encoding CNP and GC-B, respectively) lead to achondroplasia, dwarfism, female infertility and early death, and these severe growth phenotypes in mice are mirrored by the symptoms of human patients with inactivating mutations in NPR2 and NPPC mutations." (PMID 33499110, 2021).
growth disorders (3 papers, 2022 to 2023). "On the other hand, heterozygous pathogenic NPR2 variants lead to milder growth disorders, mostly classified as ISS, although some of the affected individuals might present mild signs of bone dysplasia." (PMID 35741827, 2022). "All these variants were identified in genes already associated with growth disorders: PROKR2 (N = 2), PTPN11 (N = 6), ANKRD11 (N = 1), NPR2 (N = 1), NF1 (N = 1), ACAN (N = 1), GH1 (N = 1), FBN1 (N = 1), COMP (N = 1), IGF1R (N = 1), ARID1A (N = 1), and CASR (N = 1)." (PMID 37605180, 2023). "The NPR2 signaling cascade promotes bone matrix synthesis and stimulates the proliferation and differentiation of cartilage; thus, alterations in that pathway lead to growth disorders." (PMID 35741827, 2022). "Previous studies have shown that heterozygous mutations in NPR2 appear to be associated with mild and variable growth disorders without a distinct skeletal phenotype compared with homozygous or compound heterozygous mutations in NPR2 that cause severe short stature and body disproportion." (PMID 37605180, 2023). "The defined CNP signaling pathway, the NPR2-PKG-BK channel–TRPM7 channel–CaMKII axis, likely pinpoints promising target proteins for developing new therapeutic treatments for divergent growth disorders." (PMID 35287796, 2022).
Infertility (3 papers, 2012 to 2023). "What then might cause the infertility of males bearing homozygous Npr2 mutations?" (PMID 25012822, 2014). "There may also be other explanations for the infertility of Npr2 mutant males other than physical limitations due to dwarfism." (PMID 25012822, 2014). "It is worth noting that the transmission of the mutant Npr2 gene seems to have had no apparent effect on fertility in the family, although infertility was observed in Nppc or Npr2 null or hypomorphic mice." (PMID 22870295, 2012).
Obesity (3 papers, 2013 to 2022). Accumulation of substantial excess body fat. "Our study showed clinically relevant increases in BMIs in NPR2 carriers, although further investigation, including measures of body fat, should be conducted to clarify the role of NPR2 variants in obesity risk." (PMID 35741827, 2022). "It has been reported that the C-type natriuretic peptide (CNP), for which the NPR-B is a receptor (encoded by the NPR2 gene), is a natural regulator of adipogenesis, playing a role in the development of obesity in childhood." (PMID 35741827, 2022).
overgrowth syndrome (3 papers, 2017 to 2018). A group of syndromes caused by genetic birth defects that may lead to the development of malignancies. "In contrast, NPR2 gain-of-function mutations result in an overgrowth syndrome." (PMID 29472841, 2018). "Furthermore, overproduction of C-type natriuretic peptide by chromosomal translocation and gain-of-function mutations in natriuretic peptide receptor-2 (NPR2) gene have been reported to be responsible for overgrowth syndromes or extremely tall stature without skeletal deformities." (PMID 28774346, 2017).
pituitary adenomas (3 papers, 2014 to 2019). "We have recently described the presence of both NPPC and NPR2 transcripts in normal human pituitary tissue of fetal and adult origin and in a range of pituitary adenomas including those from acromegalic patients." (PMID 24352806, 2014).
polycystic ovary syndrome (3 papers, 2021 to 2025). A disorder that manifests as multiple cysts on the ovaries. "Previous studies have indicated that the overactivated CNP/NPR2 system in follicles is involved in the formation of polycystic ovary syndrome (PCOS), which is specifically manifested by the abnormal elevation of Nppc/NPPC and Npr2/NPR2 in follicles of PCOS mouse models and human patients." (PMID 41155338, 2025).
pulmonary hypertension (3 papers, 2016 to 2026). Increased pressure within the pulmonary circulation due to lung or heart disorder. "Mice developing pulmonary hypertension (PH) show reduced pulmonary NPPC and NPR2 expression than mice without PH." (PMID 41844596, 2026).
Sepsis (3 papers, 2016 to 2024). Sepsis is defined as life-threatening organ dysfunction caused by a dysregulated host response to infection. "A recent study, utilizing both in vitro human endothelial cells and an in vivo mouse model, provided strong evidence that ruscogenin exhibits considerable efficacy in sepsis treatment and blocks specifically MIR-146a-5p and, in parallel, activates NPR2 and SSH1." (PMID 39335561, 2024).
thanatophoric dysplasia (3 papers, 2018 to 2025). A primary bone dysplasia with micromelia characterized by macrocephaly, narrow thorax, and distinctive facial features. "BMN 111, a C-type natriuretic peptide analog, inhibits FGFR signaling at the level of the RAF1 kinase through natriuretic peptide receptor 2 (NPR2) and has been shown to lengthen the long bones and improve skull morphology in the Fgfr3Y367C/+ thanatophoric dysplasia mouse model." (PMID 30048539, 2018).
chondrosarcoma (2 papers, 2017 to 2021). A malignant cartilaginous matrix-producing mesenchymal neoplasm arising from the bone and soft tissue. "Furthermore, studies of fibroblasts and chondrogenic cells derived from embryonic carcinomas and chondrosarcomas have indicated that FGF signaling decreases NPR2 activity, and that the inactivation is due to dephosphorylation of NPR2." (PMID 29199951, 2017). "With FGF treatment, the ratio of the signal in the upper versus lower regions decreased (compare lanes 1 and 2), indicating NPR2 dephosphorylation in response to FGF and confirming, with primary chondrocytes, a previous study using a rat chondrosarcoma (RCS) cell line." (PMID 33986191, 2021).
glioma (2 papers, 2017 to 2021). A benign or malignant brain and spinal cord tumor that arises from glial cells (astrocytes, oligodendrocytes, ependymal cells). "To confirm the expression and function of the natriuretic peptide system in C6 cells, we used multiplex RT-qPCR to examine the expression of Npr1, Npr2 and the glial cell marker, Gfap, in rat brain tissue and C6 glioma cells." (PMID 33672024, 2021).